TPO (thyroid peroxidase)
Diseases named in the same sentence as TPO in open-access papers (continued):
Sharing a sentence is not in itself a finding about the gene and the disease.
papillary thyroid carcinoma (continued). "This tumour type can be difficult to diagnose on H&E morphology alone, but TPO immunostaining has in recent years been supplemented with immunostaining for the cytokeratin marker, CK19, a well-known reliable positive marker of papillary carcinomas." (PMID 18031322, 2008). "The expression of serum triiodothyronine, tetraiodothyronine, thyrotropin, thyroglobulin antibody and thyroid peroxidase antibody and NDRG3 were significantly different among benign thyroid nodules, papillary thyroid carcinoma cases and healthy control groups (P <0.001)." (PMID 36619553, 2022). "In the expression and activity of TPO, 55–70% is observed in differentiated thyroid carcinoma, but in the case of anaplastic tumors, they have nonexistent TPO expression." (PMID 35571253, 2022). "After isolation, CD133+ cells exhibited higher radioresistance and higher expression of Oct4, Nanog, Sox2, Lin28 and Glut1 in the cell line or primarily cultured papillary thyroid cancer cells, and lower expression of various thyroid-specific genes, namely NIS, Tg, TPO, TSHR, TTF1 and Pax8." (PMID 23081821, 2013). "On NCB, three had been diagnosed as oxyphilic adenomas being TPO positive, and the remaining two had been diagnosed as TPO-negative papillary carcinomas." (PMID 18031322, 2008). "Moreover, treatment of TPC-1 and BCPAP cells for 24 h with trametinib, a MEK inhibitor which was shown to reduce HMGA2 mRNA expression levels, increased TG, TPO and PAX8 mRNA levels, suggesting that the MAPK pathway induces cell dedifferentiation in papillary thyroid carcinomas through HMGA2." (PMID 40004107, 2025). "Before testing anti-TPO Abs in in vivo trials, we compared the in vitro cytotoxic activities of baculovirus-expressed, CHO-expressed human IgG1 anti-TPO aAbs named B4 and B4′ with those of purified anti-TPO IgG of patients' sera, on papillary thyroid cancer cells expressing TPO." (PMID 20145622, 2010).
celiac disease (27 papers, 2014 to 2025). An autoimmune genetic disorder with an unknown pattern of inheritance that primarily affects the digestive tract. "Second, given the significant association between anti-TPO and anti-TTG positivity, screening for celiac disease should be considered in hypothyroid patients, particularly those presenting with gastrointestinal symptoms, anemia, or unexplained weight loss." (PMID 41280993, 2025). "The association between autoimmune conditions (including celiac disease, as indicated by anti-TTG positivity) and anti-TPO antibody status was assessed." (PMID 41280993, 2025). "The positive rates of thyroid peroxidase antibody (TPO-Ab), celiac disease-related transglutaminase antibody (tTG-Ab), and Addison’s disease-related 21-hydroxylase antibody (21OH-Ab) in Chinese LADA patients were 16.3%, 2.1% and 1.8%, respectively." (PMID 36090989, 2022). "Anti-TTG and anti-TPO autoantibodies have been reported in celiac disease sufferers who develop thyroid dysfunction." (PMID 29854851, 2018). "In our study, the distribution of TPO positivity at 12 years of age among the previously diagnosed celiac disease cases was equal among those diagnosed before 2 years of age and after 2 years of age." (PMID 24592326, 2014). "In addition, seven participants had AITD/TPO+ and three had a celiac disease diagnosis." (PMID 38946973, 2024). "Overall, a subset of children with celiac disease exhibited additional autoimmune markers, with GAD and anti-TPO antibodies being most frequently detected, while islet cell and ZnT8 antibodies showed lower rates of positivity." (PMID 40650029, 2025). "Apart from T1Ab negativation, some children, all younger than 3 years of age, also negativized anti-TG, anti-TPO and anti-TTG IgA, implying that reversal of seroconversion in younger children possibly provides additional protection from Hashimoto’s and celiac disease." (PMID 37238410, 2023). "However, in studies where patients with and without celiac disease were involved, the reduction in gluten intake led to diminished thyroid inflammation solely in individuals afflicted with CD, with no significant impact observed on thyroid peroxidase antibodies (anti-TPO)." (PMID 39519244, 2024).
iron deficiency (26 papers, 2010 to 2025). "Iron deficiency impairs thyroid peroxidase activity, but comorbid conditions often confound its association with AITD." (PMID 41383597, 2025). "Hepcidin synthesis is stimulated by IL-6, particularly under low-carbohydrate or energy-restricted conditions, while iron deficiency itself can limit TPO activity and T4 to T3 conversion." (PMID 41515177, 2025). "One possible mechanism is that iron deficiency impairs the heme-dependent TPO enzyme, which limits the synthesis of thyroid hormones." (PMID 39697936, 2024). "Iron deficiency causes iron deficiency anemia, which reduces the activity of thyroid peroxidase (a Fe-dependent enzyme), leading to the repression of thyroid hormone synthesis and myogenesis." (PMID 37233634, 2023). "Iron deficiency and anemia are associated with hypothyroidism probably due to the impaired biosynthesis of the hemoprotein TPO, but the central feedback regulation of the HPTP axis is also disturbed." (PMID 36834802, 2023). "Some previous studies proved that iron deficiency has multiple affects on the thyroid axis and was of crucial importance for thyroid hormone synthesis by reducing the activity of thyroid peroxidase." (PMID 36422828, 2023). "A study with human subjects confirmed a reduced activity of TPO in groups with ID (by 33–56% depending on the severity of iron deficiency)." (PMID 36364944, 2022). "Iron deficiency (ID) can reduce the activities of thyroid peroxidase and 5′-deiodinase, inhibit binding of triiodothyronine to its nuclear receptor, and cause slower utilization of T3 from the serum pool." (PMID 36364944, 2022). "Iron deficiency, the most common global trace element deficiency, adversely affects heme-containing thyroperoxidase (TPO), which catalyses initial steps of TH synthesis." (PMID 34836027, 2021). "In contrast, iron deficiency (ID) worsens preexisting thyroid dysfunction due to the decreased activity of the heme-dependent thyroid peroxidase (TPO)." (PMID 34064075, 2021). "Iron deficiency causes impairment of the heme-dependent enzyme thyroid peroxidase, thereby limiting synthesis of thyroid hormones, which can lead to a reduction in circulating levels of tT3 and tT4." (PMID 33302910, 2020). "The prevalence of positive anti-TPO Ab was higher in children with iron deficiency than iron-sufficient ones (10.5% vs 4.8%, p=0.26)." (PMID 20411676, 2010). "Iron deficiency can impair TPO activity, leading to decreased production of thyroid hormones T3 and T4, which disrupts thyroid function and may trigger compensatory increases in TSH levels." (PMID 39416653, 2024). "First, the haeme-dependent enzyme, TPO, is required for TH synthesis, so low ferritin levels, as a proxy for iron deficiency, will decrease TPO activity and may therefore contribute to impaired TH synthesis." (PMID 38330593, 2024). "One hypothesis suggests that iron deficiency may induce post-translational modifications in TPO, potentially creating new epitopes or revealing previously hidden ones, thereby enhancing TPO’s immunogenicity." (PMID 39416653, 2024). "Univariate logistic regression analysis revealed that iron deficiency was associated with an increased risk of subclinical hypothyroidism with odds ratio (OR) 8.182 (95% CI: 1.798-37.234, p=0.007) and raised anti-TPO with OR 8.77 (95% CI: 1.105-69.681; p=0.040)." (PMID 36636539, 2023). "Furthermore, iron deficiency was found to be associated with an increased risk for elevated anti-TPO (OR=8.77, 95% CI: 1.105-69.681, p=0.040)." (PMID 36636539, 2023). "A study with seven groups of rats showed that iron deficiency can reduce the activity of TPO." (PMID 36364944, 2022). "Iron deficiency can reduce the activity of thyroid peroxidase (TPO)." (PMID 36364944, 2022).
iron deficiency (continued). "Iron deficiency and iron-deficiency anemia are widespread in women and may affect thyroid function; in particular, iron deficiency decreases the iodination activity of TPO—an enzyme containing a heme group—which consequently impairs iodine organification and uptake." (PMID 41226288, 2025). "Consequently, iron deficiency impairs TPO function and thereby disrupts thyroid hormone synthesis." (PMID 41383597, 2025). "Other investigations have also revealed a link between iron deficiency (ID) and iron deficiency anaemia (IDA) with AIT and a higher prevalence of Thyroid peroxidase antibody (TPO-Ab) in women with severe to mild ID." (PMID 40071251, 2024). "Severe iron deficiency (assessed by ferritin levels) can affect TPO activity, thyroid hormone synthesis, and the peripheral conversion of T4 to T3, and it can increase TSH levels; additionally, iron deficiency has also been found to be associated with a higher prevalence of TPOAb positivity." (PMID 39337701, 2024). "Severe iron deficiency worsens preexisting thyroid dysfunction due to the decreased activity of the heme dependent TPO, and the lack of calcium and vitamin D has negative effects on bone turnover and bone health." (PMID 34064075, 2021). "Iron deficiency without anemia (ID – A) and severe iron deficiency with anemia (ID + A) rat models showed similar results that both of them could cause serum TT4 decreased as well as TPO activities reduction during pregnancy." (PMID 32351449, 2020).
Obesity (25 papers, 2018 to 2026). Accumulation of substantial excess body fat. "Overweight and obesity were associated with skin involvement at diagnosis, RF positivity, and the presence of anti-TPO-Ab and Tg-Ab." (PMID 39981087, 2025). "The association between obesity and anti-TPO or anti-TG positivity remains inconsistent across studies." (PMID 40806651, 2025). "Obesity and age at onset of (≥40 years) for psoriasis were associated with higher risk for development of TPO Ab." (PMID 31157131, 2019). "Moreover, TPO/TgAb positivity and US positivity also had a significantly association with obesity in both genders (male: OR 1.982, 95% CI 1.149, 3.420, P = 0.014; female: OR 1.601, 95% CI 1.145, 2.238, P = 0.006)." (PMID 30405316, 2018). "Moreover, TPO/TgAb (+) and US (+) were associated with an increased risk of obesity for both genders (P = 0.014 in men and P = 0.006 in women)." (PMID 30405316, 2018). "Thus, the association between obesity and TPO-Ab or Tg-Ab positivity remains inconsistent." (PMID 35395842, 2022). "Among the BMI-stratified groups, individuals with first and second-degree obesity exhibited higher anti-TPO positivity and anti-Tg titers compared with the control group." (PMID 40114573, 2026). "Psoriasis patients with late-onset (age ≥40 years) and obesity were significantly more likely to have positive TPO antibodies, with a prevalence of 42.1% and 40.7%, respectively." (PMID 35415048, 2022). "Patients with psoriasis with age of onset at diagnosis ≥40 years old and obesity were significantly more likely to have positive TPO Ab with a prevalence of (42.1% and 40.7%, respectively)." (PMID 31157131, 2019). "In the view of that, we recommend inclusions of thyroid antibodies, particularly TPO Ab, and thyroid ultrasound in the evaluation of patients with psoriasis, especially for those with late-onset psoriasis and obesity." (PMID 31157131, 2019). "Obesity and central obesity were increased by about 1.60- and 1.55-fold in the presence of both TPO/TgAb positivity and US positivity." (PMID 30405316, 2018). "According to a cross-sectional survey of 2505 individuals, obesity was significantly associated with anti-TG positivity after adjusting for sex, age, and smoking, but not with a higher anti-TPO positivity rate, which is consistent with our findings." (PMID 40806651, 2025). "It is possible that obesity contributes to the generation of both anti-TPO and anti-TG autoantibodies, although experimental models have led to the hypothesis that the production of anti-TG may occur earlier, followed by the development of anti-TPO." (PMID 40806651, 2025). "Furthermore, recent meta-analytical findings underscore a positive correlation between obesity and HT, alongside elevated levels of anti-thyroid peroxidase (anti-TPO) antibodies." (PMID 39006367, 2024). "The present study further explored the relationship between obesity and TPO-Ab or Tg-Ab." (PMID 35395842, 2022). "For men, the adjusted odds ratio of obesity increased by 98% in the TPO/TgAb (+) and US (+) group." (PMID 30405316, 2018). "Other factors that affect TSH levels include thyroid peroxidase (TPO)-antibody positivity, BMI, obesity, smoking, critical illness, and many xenobiotics, including environmental pollutants and drugs." (PMID 33716972, 2021). "Corroborating this result, obesity was significantly correlated with positive anti-TPO (RR = 1.93, 95% CI 1.31–2.85, p = 0.001) and not with anti-Tg in a meta-analysis of 22 studies." (PMID 41228508, 2025). "Other studies, however, have reported significant associations between both anti-TPO and anti-TG positivity and obesity, whereas some failed to confirm this relationship for anti-TPO." (PMID 40806651, 2025). "Therefore, it is suggested to follow the current guidelines for thyroid function testing in patients with obesity, which recommend measuring TSH, fT4, fT3, and TPO antibodies in all individuals with obesity, especially before bariatric surgery." (PMID 38526760, 2024).
thyroid nodule (24 papers, 2006 to 2025). A small circumscribed mass in the THYROID GLAND that can be of neoplastic growth or non-neoplastic abnormality. "Unlike previous studies, the dataset included standard demographic and biochemical markers (i.e., FT3, FT4, TSH, TPO, TGAb) and detailed ultrasound-derived characteristics of thyroid nodules (e.g., location, multifocality, size)." (PMID 40282484, 2025). "Participants with thyroid nodules presented a lower positive rate for anti-TG and anti-TPO, had a lower level of urine iodine, but had relatively higher pollutant concentrations." (PMID 34966357, 2021). "Malignant thyroid nodules have comparatively less iodine, due to the decreased expression of TPO mRNA and NIS, than benign thyroid nodules." (PMID 32256574, 2020). "Thyroid hormones (triiodothyronine, thyroxin, free triiodothyronine, free thyroxin, thyrotropin), thyroid autoantibodies (thyroid peroxidase antibody, antithyroglobulin antibody), and thyroid nodules (diagnosed by ultrasonography) was measured in 1271 adults." (PMID 28678169, 2017). "HBME1, CK19, CD26/DPPIV, TPO and c-met have also been reported to be useful markers for improving the preoperative characterisation of thyroid nodules." (PMID 16804521, 2006). "Positive anti-TPO was identified as an independent factor of thyroid nodule malignancy." (PMID 30258461, 2018). "At least 50 molecular markers have been analyzed in patients with thyroid nodules, and the use of immunocytochemistry for detecting abnormally high levels of thyroid peroxidase and galectin-3 in nodule FNAC seems to be particularly promising for predicting malignancy." (PMID 24597765, 2014). "Moreover, using multivariate logistic regression, positive anti-TPO was identified as an independent predictor of thyroid nodule malignancy increasing the risk 2.28 times compared to anti-TPO-negative patients." (PMID 30258461, 2018). "Previous studies have demonstrated that the expressions of TPO mRNA and NIS in malignant thyroid nodules were less than in benign lesions." (PMID 32256574, 2020). "Due to the coexistence of anti-TPO Ab and TRAb in AITD, our results imply that clinicians should be cautious when evaluating thyroid nodules in patient with positive TRAb and a relatively high serum TSH level." (PMID 28951739, 2017). "During a 5-year period 427 consecutive patients with a cold thyroid nodule were evaluated by ultrasound-guided NCB, which had been routinely stained for TPO in an automated immunostainer." (PMID 18031322, 2008). "In the present series, we compared the performance of TPO, DPP4, and HBME-1 on FNA smears obtained from 200 thyroid nodules before or after surgical resection." (PMID 18212751, 2008). "Routine measurement of serum anti-thyroid peroxidase (TPO) antibodies is not necessary for thyroid nodule evaluation." (PMID 28702251, 2016). "TPO immunostaining was found to be a valuable adjunct to morphology in the diagnosis of cold thyroid nodules of the nonoxyphilic type." (PMID 18031322, 2008). "In addition, TPO immunostaining of an NCB is a valuable additional tool in the differentiation between benign and malignant scintigraphically cold thyroid nodules of the nonoxyphilic type." (PMID 18031322, 2008).
Primary hypothyroidism (22 papers, 2012 to 2025). A type of hypothyroidism that results from a defect in the thyroid gland. "TAI is the predominant cause of primary hypothyroidism resulting from the targeting of thyroid peroxidase (TPO) or thyroglobulin (TG) by autoantibodies, which may ultimately lead to thyroid tissue destruction." (PMID 36589828, 2022). "Mutations in the TPO gene also cause congenital goitrous primary hypothyroidism." (PMID 34209805, 2021). "For patients with primary hypothyroidism, additional testing for thyroid antibodies, including thyroid peroxidase (TPO) antibody, is required." (PMID 35015209, 2022). "HT is defined as primary hypothyroidism with an atrophic thyroid gland, an increased serum level of serum thyroid peroxidase (TPO) Ab and/or blocking TSH-R-Ab (TBAb)." (PMID 33776915, 2021). "The thyroid function test indicated primary hypothyroidism with elevated antithyroid peroxidase antibodies (A-TPO), antithyroglobulin antibodies (A-Tg), and thyrotropin receptor antibodies (TRAb)." (PMID 31687021, 2019). "Our practice is to perform thyroid peroxidase antibody testing in primary hypothyroidism when Hashimoto's is suspected." (PMID 31312298, 2019). "During his evaluation for SCFE management, primary hypothyroidism was diagnosed due to the presence of anti-thyroid peroxidase and anti-thyroglobulin antibodies." (PMID 28923047, 2017). "Thyroid function testing confirmed severe primary hypothyroidism (TSH > 150 mIU/L, undetectable free T4), and high-titre thyroid peroxidase antibodies established autoimmune Hashimoto’s thyroiditis as the underlying cause." (PMID 41426848, 2025). "Such treatment makes primary hypothyroidism worse but, even if thyroidal H2O2 levels were to be further increased by TSH stimulation, this cannot overcome the PTU inhibition of thyroid peroxidase." (PMID 41086018, 2025). "You diagnose primary hypothyroidism, explain why testing for anti-TPO antibodies is not useful, and start levothyroxine, with a plan to re-check TSH and clinical status in 6–12 weeks." (PMID 40599024, 2025). "The findings showed that 45% of people with primary hypothyroidism had anti-TPO positive (+); thus, these patients were suffering from HT, and 55% of them had anti-TPO negative (˗)." (PMID 37161471, 2023). "Finding positive anti thyroid peroxidase (TPO) antibody titers supports the diagnosis of primary hypothyroidism but does not prove it." (PMID 33320308, 2021). "To further determine the clinical characteristics of patients with TPO-negative vs TPO-positive primary hypothyroidism, we performed a subgroup analysis." (PMID 32202644, 2020). "Patients with TPO antibodies had a higher likelihood of primary hypothyroidism than those without TPO antibodies (odds ratio, 7.36; 95% CI, 1.89-28.62; P = .004)." (PMID 32202644, 2020).